ALB (albumin)
Diseases named in the same sentence as ALB in open-access papers (continued):
Sharing a sentence is not in itself a finding about the gene and the disease.
cancer (continued). "Consequently, this evidence therefore aligns with results from this present study, since cancer cell growth in source B serum (with almost 3-fold greater levels of albumin compared to source A) was significantly lower in both cancer cell lines." (PMID 31683821, 2019). "Albumin (Alb), which has been commonly used to for the nutritional and inflammatory status assessment, is indicated as a potential prognostic factor for advanced cancer." (PMID 31533857, 2019). "Numerous studies have also shown that low albumin level is associated with increased RDW level in cancer patients 24,60,30,69, which also indicated the relationship between high RDW level and poor nutritional status in patients with cancer." (PMID 31413750, 2019). "Albumin versatility in accommodating different payloads and in being modified with simple “click-chemistry” methods, make this protein an eligible candidate for developing universal nanomedicine to treat cancer and other pathological conditions." (PMID 31195727, 2019). "Albumin is frequently used as a biomarker of nutritional and inflammatory processes in cancer." (PMID 30634387, 2019). "Albumin is closely related to inflammatory responses in cancer patients." (PMID 31312573, 2019). "Albumin has a number of characteristics that make it an attractive drug vehicle or primer, including the ability of the protein to carry hydrophobic drugs, such as paclitaxel, through the blood and deliver them directly to cancer cells." (PMID 30941174, 2019). "Furthermore, docetaxel and rapamycin loaded in albumin to achieve other albumin-based drugs for cancer treatment, which are advancing into clinical trials." (PMID 31526064, 2019). "The results of the present systematic review show that in approximately 10,000 patients with cancer, there was a consistent association between CT-derived SMI/SMD and systemic inflammation, as evidenced by CRP, albumin (mGPS) and Neutrophil Lymphocyte Ratio (NLR)." (PMID 31487957, 2019). "Albumin is also related to the cancer cell-induced inflammatory reaction." (PMID 30718566, 2019). "Taken together, these results showed that albumin-based DOXO-loaded nanoparticles might represent a novel platform to overcome the mechanism of drug resistance in cancer cell lines and improve the efficacy of the chemotherapy." (PMID 30669702, 2019). "Studies have also demonstrated that high fibrinogen and low albumin levels could predict the prognosis of patients with several types of cancers." (PMID 31781312, 2019). "A cancer panel was designed in-house based on data published previously to analyze the noncoding regions of six genes—surfactant protein A1, B, and C, as well as albumin, lipase, and thyroglobulin." (PMID 30999697, 2019). "Albumin, is another important independent prognostic factor for many cancers, including HCC." (PMID 31164099, 2019). "Following multivariate analysis, male sex (OR=2.12; 95%CI: 1.32-3.40), cancer (OR=7.36; 95%CI: 4.26-13.03), advanced dementia (OR=12.6; 95%CI: 7.5-21.2), and albumin levels (OR=0.25; 95%CI: 0.17-0.38) were identified as independent predictors of referral to exclusive palliative care." (PMID 29694607, 2018). "The hemoglobin and albumin abnormalities might be due to the generalized nutritional and functional decline common in cancer and/or reflect the secondary effects of a high inflammatory load." (PMID 30138391, 2018). "This strategy was demonstrated by the site‐selective conjugation of NHC*−Au−Cl to albumin and the antibody trastuzumab with the aim of enhancing stability and blood circulation half‐time as well as biodistribution to cancer tissues of the gold‐based anticancer drug." (PMID 29729206, 2018). "Secondly, CRP/ALB ratio for cancer patients should also be considered." (PMID 29495423, 2018). "For this goal, we hypothesized that albumin fragments based NPs could have better drug loading/release performance, which would result improved anti-cancer performance." (PMID 29946256, 2018).
cancer (continued). "TGUG, albumin, age, handgrip, and BMI were associated positively with cancer, whereas eGFR and hemoglobin had a negative association in the PC patients." (PMID 29707115, 2018). "We have demonstrated that plasma redox imbalance caused by albumin oxidation triggers NETosis and cancer metastasis without massive inflammation." (PMID 30504805, 2018). "Thus, numerous studies have suggested that pretreatment serum ALB can be an effective prognostic indicator for cancer patients, as the low level of serum ALB predicts the worse prognosis." (PMID 29568406, 2018). "For instance, additional studies are needed to carefully characterize the relationship between distinct types and stages of human cancer, plasma free thiol levels, albumin redox status, NET markers, environmental and treatment exposures, and sites of cancer metastasis." (PMID 30504805, 2018). "In the non-PC patients, male sex, TGUG and age were positively associated with cancer, whereas handgrip, eGFR, albumin, and hemoglobin had a negative association." (PMID 29707115, 2018). "Overall, the VE-Albumin core-shell nanoparticles could be a promising nanocarrier for PTX delivery to improve the chemotherapeutic efficacy of MDR cancer." (PMID 30366367, 2018). "Furthermore, numerous studies have suggested that the lower the level of serum ALB, the worse the prognosis of cancer patients." (PMID 29568406, 2018). "Various nanocarriers have been developed for the co-delivery of anti-cancer drugs and P-gp inhibitors, such as the co-delivery of paclitaxel and borneol in lipid-albumin nanocomplex, docetaxel and verapamil in polymeric micelles, and paclitaxel and curcumin in lipid-albumin hybrid nanoparticles." (PMID 30366367, 2018). "The CRP/ALB ratio was initially used as a novel prognostic factor in patients with cancer." (PMID 29495423, 2018). "Experiments were carried out with first through third generations of these patched surface dendrimers to bind 16-DOXYL-stearic acid, a spin-labeled fatty acid, and complex doxorubicin (anti-cancer therapeutic drug), as compared to human serum albumin (HSA), a naturally occurring HSA protein." (PMID 30363718, 2018). "In addition to local inflammatory symptoms, cancer patients frequently present with systemic inflammation responses, including increased peripheral blood cell amounts and decreased serum albumin levels." (PMID 30116261, 2018). "A striking example is albumin which binds oleic acid in blood without reports of associated anti-cancer activity, yet forms a cytotoxic BAMLET complex with oleic acid when prepared using a BAMLET heating protocol." (PMID 30157247, 2018). "The globulin‐to‐albumin ratio (GAR) is useful for prognostication of patients with various cancers." (PMID 30238078, 2018). "Albumin, AGR, and PNI are all associated with nutritional status in patients with cancer." (PMID 30154718, 2018). "Oxidation of albumin thiols within the plasma of cancer patients may occur through multiple mechanisms." (PMID 30504805, 2018). "In addition, inflammation, which is a critical step in cancer initiation and progression, can alter the levels of serum albumin." (PMID 29685957, 2018). "It was reported that cancer patients with low BMI was always accompanied by low hemoglobin and albumin levels which may due to poor nutritional status and cachexia." (PMID 29409475, 2018). "Thus, assessment of serum ALB has emerged as a potential prognostic factor in various cancers, since nutritional status can be corrected prior to therapy." (PMID 29568406, 2018).
cancer (continued). "According to the prognostic association between PNI and albumin and lymphocyte counts, it seems that PNI is a reflection of systemic inflammation, which may influence cancer growth and metastasis." (PMID 28842710, 2017). "However, to our knowledge, no study so far has assessed the clinical significance of the NLR/Albumin (NLR/Alb) ratio in other cancers as well as EC." (PMID 29262582, 2017). "Albumin nanoparticles as carriers for targeted delivery of chemotherapeutic drugs, have attracted much attention due to the fact that they increase endocytic uptake of the drugs by rather cancer cells than normal cells." (PMID 29186208, 2017). "Albumin/AlbiVax nanocomplexes are thus a robust platform for combination cancer immunotherapy." (PMID 29203865, 2017). "As such, the albumin-carried SNPs appear to be absorbed stronger by cancer cells than normal cells." (PMID 28701707, 2017). "We hypothesize that neutrophils and lymphocytes may play more important roles in cancer progression and prognosis than monocytes, platelets, and albumin, which may partly explain our results, although these results need to be confirmed." (PMID 29126400, 2017). "Additionally, serological tests showed that participants in the cancer group had lower serum albumin levels (3.85 ± 0.36 vs. 4.12 ± 0.27, P = 0.004)." (PMID 29017525, 2017). "Since our molecular analyses indicated an activation of stemness in the SL region, we next assessed the gene expression levels of specific HCC/differentiation markers (AFP, GPC3, albumin) as well as the selected (cancer-) stemness markers (EpCAM, CD133, CK19) and pluripotency genes (NANOG)." (PMID 28415775, 2017). "As such, an albumin-carried drug appears to be absorbed by cancer cells more than by normal cells." (PMID 28701707, 2017). "Although the prognostic value of the pretreatment albumin level and fibrinogen level have been established in patients with cancers, the mechanisms responsible for these associations are unknown." (PMID 28548947, 2017). "Additionally, the growth of many cancer cell lines can be inhibited by high concentrations of albumin." (PMID 28654895, 2017). "Furthermore, treatment of CIS significantly decreased plasma albumin levels (p < 0.001) as compared to cancer control animals." (PMID 28420987, 2017). "The aim of this study was to investigate whether all liver parameters including BChE and albumin have the ability to predict long-term mortality in a treatment naïve cancer patient cohort independently from a malignant hepatic involvement." (PMID 29113384, 2017). "Third, as a chronic consumption disease, NSCLC may lead to albumin catabolism during cancer progression as well as nutrition absorption disorders." (PMID 29137238, 2017). "Previous studies investigated that C-reactive protein (CRP) and albumin levels may represent potential prognostic markers in various cancers." (PMID 28740506, 2017). "Recent studies have shown that macropinocytosis of circulating proteins (especially albumin) could supply amino acids to nutrient-deprived cancer cells." (PMID 26920219, 2016). "Furthermore, the cRGD-conjugated albumin nanoparticle platform in this study paves a new way for smart delivery of other anticancer drugs to human cancers." (PMID 27515795, 2016). "In the NHANES III study and another study within the AMORIS cohort, a quantitative score, ranging from 0-4, derived by adding a number of biomarkers (CRP, albumin, gamma-glutamyl transferase, and HDL cholesterol) with abnormal values was positively associated with cancer mortality." (PMID 26860264, 2016). "Increased PLR together with decreased albumin, which indicates hypoimmunity in patients, may lead to cancer." (PMID 26885692, 2016). "Thus, hypoalbuminemia is uncommon in early-stage cancer but as the disease progresses, albumin levels drop significantly and serve as good prognostic indicators in patients with various cancers." (PMID 26880857, 2016).
cancer (continued). "The re-adhesion rate (as an aspect of the metastatic process inhibited by NAMI-A) of cancer cells was reported to be only slightly (though significantly) less reduced when NAMI-A is applied in albumin-bound form in vitro, suggesting that biological activity is basically maintained." (PMID 26988975, 2016). "We hypothesized that merging CRP and albumin into a new index may have prognostic value in inflammation, and better predict overall survival of patients with cancer." (PMID 26084991, 2015). "In recent years, the Glasgow Prognostic Score (GPS), which consists of two predictors, namely, C-reactive protein (CRP) and albumin, has been found useful for predicting long-term mortality primarily in cancer patients in the outpatient or pre- and postsurgical settings." (PMID 25861154, 2015). "In addition, in cancer patients with advanced cancer and during the fasting state, the total albumin synthesis rate is unchanged, compared with controls, despite much lower albumin concentrations." (PMID 26523094, 2015). "Additionally, nutritional status, which is commonly evaluated using serum albumin levels, is an important prognostic factor in advanced cancer." (PMID 26356222, 2015). "For this reason, cancer patients frequently present changes in various systemic parameters, comprising alterations in the level of serum inflammatory cytokines, acute-phase proteins and total albumin." (PMID 25653573, 2015). "Exact information about cancer-stage is generally not available in a preoperative setting, which make global indicators, like preoperative weight loss and serum-albumin, important in recognizing advanced disease." (PMID 26148685, 2015). "Nab-paclitaxel accumulates in cancer cells due to their increased ability to engulf albumin." (PMID 24912774, 2014). "In contrast, a patient aged <60 years who has normal serum albumin and ALP levels may have a low probability that the IWL is associated with cancer." (PMID 24762986, 2014). "Additionally, we showed a significantly higher hsCRP level and significantly lower concentrations of total protein, albumin, and hemoglobin in cancer patients." (PMID 25049439, 2014). "Moreover the affinity of albumin for caveolin-1 is believed to target the drug specifically to cancer cell populations expressing high levels of this surface protein." (PMID 25015569, 2014). "Regarding measurement of the systemic inflammatory response, the combination of C-reactive protein (CRP) and albumin (ALB) may be useful for diagnosing not only chronic inflammation but also nutritional status in cancer patients." (PMID 25022764, 2014). "Low circulating albumin levels are associated with increased mortality from vascular, nonvascular, and cancer causes, both in apparently healthy persons and acutely ill patients." (PMID 24586121, 2014). "Hence, it has been suggested that tumors utilize albumin as a source of energy, by breaking down albumin into its component amino acids in lysosomes that are subsequently used by cancer cells for their accelerated growth." (PMID 25161624, 2014). "In the model predicting cancer or death, age and albumin were also retained." (PMID 23875619, 2013). "It has been also reported that serum albumin participate in systemic inflammatory response and that decline of its serum level is a poor prognostic factor for long-term survival in patients with various cancers." (PMID 23374755, 2013). "Studies have suggested that albumin is a potential biomarker for survival of cancer." (PMID 23557354, 2013). "Based on these reports, GPS, incorporating CRP and serum albumin levels, may reflect both presence of the systemic inflammatory response (CRP), and the progressive nutritional decline (albumin) in patients with cancers, resulting in poor survival outcome." (PMID 23374755, 2013).
cancer (continued). "Kras also regulates other key cellular functions related with the elevated energy needs to cancer: macropinocytosis, induced by oncogenic Kras, allows the cancer cells to acquire albumin from the surrounding extracellular space, and use it to produce Krebs cycle intermediates." (PMID 24478710, 2013). "Albumin conjugated PLGA nanoparticles may represent a promising drug delivery system in cancer therapy." (PMID 23866721, 2013). "The version of this score developed to predict cancer or death included age, albumin level, comorbidity, previous episode of VTE, and recent surgery [AUC = 0.72 (95% CI 0.66-0.78) and 0.71 (95% CI 0.63-0.79) in the derivation and validation cohorts, respectively]." (PMID 23875619, 2013). "Albumin has previously been shown to be related to the prognosis of cancer patients." (PMID 22559838, 2012). "We found that MA3 could specifically bind to MUC1-positive cancer cells, with minimal cross reactivity to albumin." (PMID 22384115, 2012). "Studies had shown that low serum albumin concentrations in malnourished older patients with advanced cancer resulted in a low clearance of highly albumin-bound drugs which, in turn, caused increased free drug concentration and contributed to unexpected toxicity." (PMID 21845189, 2011). "Nanotechnology is offering new products, which either used alone, due to their intrinsic properties, or in combination with other biomolecules (anti-tumoral drugs, folic acid, albumin, antibodies, aptamers) could be used to target cancer cells." (PMID 24212956, 2011). "Moreover, numerous fragments of albumin and of alpha-1-antitrypsin were detected in the urine of children with cancer." (PMID 22047044, 2011). "It has been shown that apolipoprotein B (apoB) and apoE rich lipoproteins are taken up by a receptor-mediated pathway in primary podocytes isolated from a human carcinoma kidney, and recently albumin was shown to be endocytosed by human podocytes in vitro and in vivo." (PMID 21949853, 2011). "All studies found pretreatment serum albumin to be prognostic of cancer survival." (PMID 21176210, 2010). "Pretreatment serum albumin levels provide useful prognostic significance in cancer." (PMID 21176210, 2010). "In summary, pretreatment serum albumin levels provide useful prognostic significance in cancer." (PMID 21176210, 2010). "As a result, it is reasonable to investigate whether serum albumin has utility as a prognostic indicator of cancer survival in cancer." (PMID 21176210, 2010). "A critical gap for demonstrating causality, however, is the absence of clinical trials demonstrating that raising albumin levels by means of intravenous infusion or by hyperalimentation decreases the excess risk of mortality in cancer." (PMID 21176210, 2010). "A study done to identify potential factors affecting survival in patients with advanced cancer in a local palliative care unit found age, number of involved metastatic sites, serum albumin, PS score, and Edmonton Symptom Assessment System score were independent prognosticators." (PMID 21176210, 2010). "Low serum albumin has also been shown to be an independent indicator for prognosis in cancer patients with unknown primaries." (PMID 21176210, 2010). "Furthermore, combination of UICC stage, serum CEA and albumin levels as predictors of cancer-specific survival showed that the poorer the prognostic factors involved, the poorer the cancer-specific survival rate." (PMID 19691850, 2009). "Moreover, serum albumin measurement is part of the liver function test battery, and for most patients it is measured even before cancer is diagnosed and before the staging protocol or the treatment program." (PMID 19691850, 2009). "The possible explanation for the association between low serum albumin and poor survival in CRC patients might be due to cancer cachexia." (PMID 19691850, 2009).